PABPC1 (poly(A) binding protein cytoplasmic 1)
Diseases named in the same sentence as PABPC1 in open-access papers (continued):
Sharing a sentence is not in itself a finding about the gene and the disease.
hepatocellular carcinoma (10 papers, 2012 to 2025). A malignant tumor that arises from hepatocytes. "Abnormally expressed PABPC1 has been found in many human malignancies, including esophageal squamous cell carcinoma, hepatocellular carcinoma, and GC." (PMID 37225681, 2023). "PABPC1, an oncogene in hepatocellular carcinoma, induces cell proliferation by promoting tumor cells into S phase and enhancing anchorage-independent growth." (PMID 36531055, 2022). "The specific mechanism is that PABPC1 interacts with AGO2 in the cytoplasm of hepatocellular carcinoma cells, and this interaction increases the recruitment of mRNA to RISC and represses multiple oncogenes." (PMID 36531055, 2022). "PABPC1 acts as an oncogene in hepatocellular carcinoma, accelerating cell proliferation and promoting anchorage-independent growth by promoting cell entry into S and G2/M phases." (PMID 36531055, 2022). "PABPC1 was found to be highly expressed in hepatocellular carcinoma, especially in high-grade hepatocellular carcinoma." (PMID 36531055, 2022). "In hepatocellular carcinoma, PABPC1 interacts with AGO2 to augment miRNA repression by facilitating RISC binding and enhancing miRNA-mediated deadenylation, leading to the inhibition of tumor suppressor genes." (PMID 35346324, 2022). "Cytoplasmic poly A binding protein (PABPC1) is significantly highly expressed in a variety of tumors, especially in ovarian, breast, gastric and hepatocellular carcinomas." (PMID 36531055, 2022). "Therefore, circDDX21 exerts its tumor-promoting effect by regulating the ubiquitination of PABPC1 to elevate the level of PGAM1 protein in hepatocellular carcinoma (HCC) cells." (PMID 41169378, 2025). "However, in other studies, PABPC1 over-expression was described in prostate tumors, hepatocellular carcinoma, superficial bladder cancer, and lung cancer; in the latter report the authors suggested the participation of the translation initiation complex in the tumorigenesis of lung cancer." (PMID 22876301, 2012). "Furthermore, SNHG14 can upregulate PABPC1 via H3K27 acetylation, regulating the PTEN signalling pathway in hepatocellular carcinoma cells while promoting cell proliferation and angiogenesis." (PMID 40521987, 2025).
prostate carcinoma (9 papers, 2015 to 2023). A carcinoma that arises from epithelial cells of the prostate gland. "In silico analysis of several publicly available datasets including the MSKCC cBioPortal for Cancer Genomics database revealed PABPC1 up-regulation in prostate cancer specimens and this up-regulation was associated with rapid disease recurrence." (PMID 26176602, 2015). "The up-regulated expression of PABPC1 in prostate cancer specimens and the association of high-level PABPC1 expression with recurrent prostate cancer further suggest that PABPC1 plays an important role in promoting prostate cancer progression." (PMID 26176602, 2015). "Polyadenylate-binding protein 1 (PABPC1) expression is associated with prostate cancer." (PMID 33114768, 2020). "Co-IP of PABPC1 using an anti-ERG antibody in TMPRSS2/ERG-positive VCaP prostate cancer cells demonstrated that endogenous ERG-bound PABPC1." (PMID 37956771, 2023). "PABPC1 can function to regulate the nuclear localization of AR, and knockdown of PABPC1 reduces AR-positive prostate cancer cell proliferation and transactivation of AR target genes." (PMID 37956771, 2023). "Further research is necessary to determine if a similar approach would change the ability of PABPC1 to promote ERG function in prostate cancer." (PMID 37956771, 2023). "This suggested that PABPC1 plays a role in the proliferation of AR-positive prostate cancer cells including castration-resistant C4-2 cells." (PMID 26176602, 2015). "PABPC1 appears to play important roles in AR function in both androgen-sensitive and castration-resistant prostate cancer cells." (PMID 26176602, 2015). "Elevated expression of PABPC1 in prostate cancer specimens is likely to play an important role in prostate carcinogenesis by enhancing AR signaling pathways." (PMID 26176602, 2015). "In silico analysis of gene expression data revealed PABPC1 up-regulation in prostate cancer tissue specimens and this up-regulation correlates to increased disease recurrence." (PMID 26176602, 2015). "Multiple studies showed that PABPC1 was up-regulated in prostate cancer specimens compared with normal controls." (PMID 26176602, 2015). "Western blot analysis showed that PABPC1 is expressed in all the tested cells with slightly higher expression in AR-positive prostate cancer cells." (PMID 26176602, 2015). "In silico analysis of the Oncomine database revealed that PABPC1 is up-regulated in prostate cancer tumor samples." (PMID 26176602, 2015). "Identification of PABPC1 as a co-factor of the AR provides a potential link between AR activity and active translation in prostate cancer cells." (PMID 26176602, 2015). "Knockdown of PABPC1 decreased AR transcriptional activity and also reduced nuclear AR in C4-2 prostate cancer cells." (PMID 26176602, 2015). "This study identified PABPC1 as a novel AR co-regulator capable of modulating AR function and subcellular localization in prostate cancer cells." (PMID 26176602, 2015). "Further functional characterization suggests that PABPC1 plays an important role in modulating AR nucleocytoplasmic localization and function in prostate cancer cells." (PMID 26176602, 2015). "knockdown of PABPC1 inhibited the proliferation of AR-positive prostate cancer cells." (PMID 36531055, 2022). "Future studies aimed at defining the precise mechanism of PABPC1 regulation of AR signaling may lead to new approaches to prevent and/or treat prostate cancer patients." (PMID 26176602, 2015). "However, a role of PABPC1 has been previously reported in prostate cancer cells." (PMID 37956771, 2023). "As such, PABPC1 may be a viable therapeutic target for ETS-positive prostate cancer." (PMID 37956771, 2023). "Thus, elevated PABPC1 expression levels in prostate cancer cells can simultaneously enhance translation and androgen action, which may lead to more efficient cell growth." (PMID 26176602, 2015).
prostate carcinoma (continued). "We have previously shown that expression of ERG can promote migration of PC3 prostate cancer cells, and migration of PC3-ERG cells was also decreased by PABPC1 knockdown." (PMID 37956771, 2023). "From this list, PABPC1, CLIC1, RAB10, and PKM2 have been identified as a potential marker for (prostate) cancer." (PMID 31018022, 2019). "Prostate cancer cells (PC3, C4-2, LNCaP, and 22Rv1) and normal prostate stromal fibroblasts (WPMY-1) were examined to determine the relative expression levels of PABPC1." (PMID 26176602, 2015). "PABPC1 modulation of the AR is likely to have a significant impact on prostate cancer progression because the AR is a key factor regulating prostate cancer cell growth and factors capable of modulating AR function could have profound effects in modulating prostate cancer cell growth." (PMID 26176602, 2015). "Furthermore, knockdown of PABPC1 reduced the interaction between ERG and EWS in prostate cancer cells." (PMID 37956771, 2023). "Additionally, knockdown of PABPC1 inhibited transactivation of the PSA promoter by NAR (AR lacking the LBD) and attenuated proliferation of AR-positive prostate cancer cells." (PMID 26176602, 2015). "Furthermore, PABPC1 knockdown inhibited proliferation of all the tested AR-positive but not the AR-negative PC3 prostate cancer cells." (PMID 26176602, 2015). "However, its influence on prostate cancer cell growth is likely mediated through the AR because PABPC1 knockdown inhibited proliferation of AR-positive prostate cancer cells, but not AR-negative PC3 cells." (PMID 26176602, 2015).
cardiac hypertrophy (8 papers, 2017 to 2025). "Another DTU gene, Pabpc1, encodes polyadenylate [poly(A)]–binding protein cytoplasmic 1, which promotes ribosome recruitment and translation initiation, and poly(A) tail shortening and is important for the increased translation seen during cardiac hypertrophy." (PMID 38905342, 2024). "Transgenic overexpression of PABPC1 in adult hearts is sufficient to drive global protein synthesis and cardiac hypertrophy in mice." (PMID 40869184, 2025). "In contrast, the poly(A) tail length on the Pabpc1 mRNA and the expression level of the PABPC1 protein are restored in adult hearts during cardiac hypertrophy." (PMID 40869184, 2025). "We show that Pabpc1 poly(A) tail length and protein expression are restored during adult-onset cardiac hypertrophy stimulated by endurance exercise or heart disease." (PMID 28653618, 2017). "Now, in eLife, Auinash Kalsotra of the University of Illinois and co-workers – including Sandip Chorghade and Joseph Seimetz as joint first authors – reveal an unexpected role for an RNA-binding protein called PABPC1 in cardiac hypertrophy." (PMID 28653621, 2017). "Our findings identify PABPC1 as a direct regulator of cardiac hypertrophy and define a new paradigm of gene regulation in the heart, where controlled changes in poly(A) tail length influence mRNA translation." (PMID 28653618, 2017). "Increased expression of PABPC1 in cardiomyocytes can induce physiological cardiac hypertrophy." (PMID 37215497, 2023). "Indeed, key components of the cytoplasmic polyadenylation complex, such as PABPC1 and CPEB4, are involved in cardiac hypertrophy." (PMID 37569379, 2023).
lung carcinoma (8 papers, 2012 to 2026). "E3 ligase MKRN3 is a tumour suppressor regulating PABPC1 ubiquitination in non‐small cell lung cancer, and PABPC1 signalling controlled the secretion of miR‐19a‐3p by CD8 T cells." (PMID 36822595, 2023). "Accordingly, PABPC1 is an RNA-binding member of the eIF4F complex responsible for the circularization of the mRNA before binding of the ribosomal subunits and has been found upregulated in lung cancer and in interaction with AGO2, which plays a key role in miRNA-mediated gene silencing." (PMID 33092114, 2020). "To further determine the expression of these hub RBPs in LUAD, we used immunohistochemistry results from the Human Protein Atlas database to show that IGF2BP1, PABPC1, and GAPDH were significantly increased in lung cancer compared with normal lung tissue." (PMID 32087603, 2020).
glioma (7 papers, 2020 to 2023). A benign or malignant brain and spinal cord tumor that arises from glial cells (astrocytes, oligodendrocytes, ependymal cells). "Studies have reported that the lncRNA BDNF-AS interacts with PABPC1 to repress the proliferation, migration, and invasion of glioma cells and the lncRNA PAGBC synergizes with PABPC1 to promote the development and progression of gallbladder cancer." (PMID 37225681, 2023). "It is known that PABP1 participates in the initiation of translation and stabilization of mRNA and that PABPC1 can encode PABP1 protein and promote tumor progression of gliomas and hepatocellular carcinomas." (PMID 34151731, 2021). "We further examined the expression levels of PABPC1 in human glioma tissues (GT) and cell lines by qRT-PCR and western blot." (PMID 32015336, 2020). "PABPC1 can be used to predict the clinical outcome of glioma patients." (PMID 34335239, 2021). "The expression and functional roles of PABPC1 in glioma remain unknown." (PMID 32015336, 2020). "Based on evidence from the Chinese Glioma Genome Atlas (CGGA) data set, PABPC1 is expressed at the lowest levels in GBM, which was validated by evidence from the TCGA." (PMID 37506150, 2023). "In summary, we first found that PABPC1, BDNF-AS, and DLG5 were downregulated in human glioma tumors and cells, while RAX2 was upregulated conversely." (PMID 32015336, 2020). "Our findings first revealed that PABPC1/BDNF-AS/RAX2/DLG5 module plays an important role in glioblastoma cells, provided insight into potential therapeutic targets to treat glioma." (PMID 32015336, 2020). "Therefore, we proposed that BDNF-AS might be involved in the regulation of PABPC1 on glioma cells." (PMID 32015336, 2020). "In our study, we provided the endogenous expression and functions of PABPC1, BDNF-AS, RAX2, and DLG5 in human glioma tumor specimens and cells." (PMID 32015336, 2020). "In general, this study elucidated that the PABPC1-BDNF-AS-RAX2-DLG5 mechanism may contribute to the anticancer potential of glioma cells and may provide potential therapeutic targets for human glioma." (PMID 32015336, 2020). "PABPC1 expressed lower in GT and cells than in surrounding nonneoplastic tissues (ST) and NBTs, and the expression level was negatively correlated with the histopathological grades of gliomas." (PMID 32015336, 2020). "Among them, the mice carrying the combined treatment produced the significantly smallest tumors and had the highest survival, suggesting that the combination of PABPC1 overexpression and BDNF-AS overexpression could be potentially applied in the treatment of glioma." (PMID 32015336, 2020).
ovarian carcinoma (7 papers, 2011 to 2025). A malignant neoplasm originating from the surface ovarian epithelium. "PABPC1 acts as an oncogene promoting the growth and invasion of ovarian cancer cells in ovarian cancer partly through regulation of the EMT process." (PMID 36531055, 2022). "This research aimed to probe the expression characteristics of poly(A)-binding protein cytoplasmic 1 (PABPC1) and its role on the phenotype of ovarian cancer (OC) cells and to further investigate the possible underlying mechanism." (PMID 34027108, 2021). "Investigating the interplay of DDX3X with PABPC1 could better explain the role of DDX3X in liver cancer as well as define its implication in ovarian cancer." (PMID 35954483, 2022). "PABPC1 is highly expressed in hepatocellular carcinoma and ovarian cancer." (PMID 35954483, 2022). "In ovarian cancer, YBX1 recognizes m5C-modified CHD3 mRNA and maintains its stability by recruiting the RNA-binding protein PABPC1, thereby enhancing homologous recombination (HR) repair and promoting resistance to platinum-induced apoptosis." (PMID 40819060, 2025). "Based on microarray studies of different cell lines, the proteins HNRPL, PABPC1, RPS4X, RPS7, and RALY are overexpressed in ovarian cancer cells resistant to oxaliplatin." (PMID 22118625, 2011).
esophageal squamous cell carcinoma (6 papers, 2020 to 2025). Esophageal squamous cell carcinoma (ESCC) is a type of esophageal carcinoma (EC) that can affect any part of the esophagus, but is usually located in the upper or middle third. "Simultaneously, the upregulation of PABPC1 promoted malignant progression in ovarian cancer, hepatocellular carcinoma, and esophageal squamous cell carcinoma (ESCC)." (PMID 36803974, 2023). "The abnormally expression of PABPC1 was found in many human malignancies, such as esophageal squamous cell carcinoma (ESCC), CC, colorectal cancer, and gastric cancer." (PMID 32015336, 2020). "Previous studies have indicated that in esophageal squamous cell carcinoma, PABPC1 fosters both angiogenesis and malignant progression by inducing IFI27 mRNA stability, and PABPC1 de‐ubiquitinated by USP10 promotes the stability of CLK2 mRNA to facilitate the development of pancreatic cancer." (PMID 40013670, 2025).
glioblastoma (6 papers, 2014 to 2024). The most malignant astrocytic tumor (WHO grade IV). "PABPC1-induced stabilization of BDNF-AS helps the inhibition of malignant progression in glioblastoma cells." (PMID 37655066, 2023). "In this study, we confirmed that lncRNA brain-derived neurotrophic factor antisense (BDNF-AS) was downregulated in glioblastoma tissues and cells, interacted and stabilized by polyadenylate-binding protein cytoplasmic 1 (PABPC1)." (PMID 32015336, 2020). "Silencing of BDNF-AS counteract the effect of the overexpression of PABPC1 on cell proliferation, migration, invasion, and apoptosis, implied that BDNF-AS is associated with the PABPC1-induced effects on glioblastoma cells." (PMID 32015336, 2020). "The proliferation ability of glioblastoma cells was decreased in the PABPC1(+) group, while increased in the PBAPC1(−) group compared with their nonspecific control (NC) group, respectively." (PMID 32015336, 2020). "On the contrary, PABPC-1 is considered as a tumor suppressor in glioblastoma cells by binding to BDNF-AS." (PMID 33584809, 2020). "Overexpression of PABPC1 significantly increased the apoptosis ratio of glioblastoma cells and inhibited the migration and invasion capability in glioblastoma cells." (PMID 32015336, 2020). "Overexpression of PABPC1 inhibited cell proliferation, migration, and invasion, while promoted apoptosis in glioblastoma cells; knockdown PABPC1 produced the opposite effect." (PMID 32015336, 2020). "We demonstrated for the first time that the PABPC1/BDNF-AS/RAX2/DLG5 pathway plays the vital role in regulating the malignant biological behaviors of glioblastoma cells." (PMID 32015336, 2020). "Moreover, we revealed that tumor-suppressive effects of PABPC1 were mediated by BDNF-AS in glioblastoma cell lines by a series of assays." (PMID 32015336, 2020). "Since PABPC1 and BDNF-AS were both downregulated and act as tumor suppressors in glioblastoma cells, we wondered whether PABPC1 would exert direct action on BDNF-AS." (PMID 32015336, 2020). "Overexpression of PABPC1 and BDNF-AS inhibited the cell proliferation, migration and invasion, and promoted apoptosis of glioblastoma cells." (PMID 32015336, 2020). "Overexpression of PABPC1, BDNF-AS, and DLG5 along with depletion of RAX2 inhibited malignant biological behaviors of glioblastoma cells." (PMID 32015336, 2020). "PABPC1 interacted with BDNF‐AS and increased its expression by stabilizing the expression of BDNF‐AS, and overexpression of both inhibited proliferation, migration and invasion of glioblastoma and promoted apoptosis." (PMID 38683130, 2024).
esophageal cancer (5 papers, 2012 to 2023). A primary or metastatic malignant neoplasm involving the esophagus. "Analyses of the expression levels of all RBPs in the esophageal cancer database from The Cancer Genome Atlas (TCGA) revealed higher PABPC1 expression in ESCC tissue than in normal esophageal epithelial tissue." (PMID 35346324, 2022). "One study concluded that low levels of PABPC1 correlated with more invasive tumors and worse survival rates in patients with esophageal cancer." (PMID 22876301, 2012). "However, for esophageal cancer it has been shown that reduced expression of PABPC1 correlates with tumor progression and poor prognosis after surgery, indicating a complex relationship between PABPC1 expression levels and cancer." (PMID 37296477, 2023). "There is increasing evidence that PABPC1 is aberrantly expressed in a variety of tumor tissues and cancers such as lung, gastric, breast, liver, and esophageal cancers, and PABPC1 might be used as a potential biomarker for tumor diagnosis, treatment, and clinical application in the future." (PMID 36531055, 2022).
gallbladder cancer (5 papers, 2019 to 2024). "PABPC1 was able to stabilize lncRNA‐PAGBC in gallbladder cancer, and activates the AKT/mTOR pathway to promote tumour growth and metastasis." (PMID 38683130, 2024). "For example, PABPC1 promotes the proliferation and metastasis of gallbladder cancer cells by enhancing PAGBC stability." (PMID 31186064, 2019). "In gallbladder cancer (GBC), PABPC1 was demonstrated to regulate tumorigenesis in GBC cells by interacting and stabilizing lncRNA-PAGBC22." (PMID 32015336, 2020).
liver cancer (4 papers, 2020 to 2025). An epithelial or non-epithelial malignant neoplasm that arises from the liver. "The results demonstrated that the expression of FCER1G, PFN1, ACTG1, PABPC1, CALM1, and RPS8 was significantly upregulated in the liver cancer cells, whereas KLRB1, LDB2, and FYN exhibited the opposite trend." (PMID 37397471, 2023).